INS (insulin)
Diseases named in the same sentence as INS in open-access papers (continued):
Sharing a sentence is not in itself a finding about the gene and the disease.
type 2 diabetes (continued). "For example, adipsin, an adipokin synthesized in the adipose tissue and released into circulation, increases insulin secretion in response to glucose, preserves ß‐cells in diabetic mice, and is associated with protection from type 2 diabetes in humans." (PMID 40243327, 2025). "Type 2 diabetes is frequently associated with elevated insulin levels, which can hinder weight loss." (PMID 41515225, 2025). "Repetitive transcranial magnetic stimulation (rTMS) can significant improve insulin sensitivity in rats with type 2 diabetes, accompanied by weight loss." (PMID 39439134, 2025). "Insulin secretion from pancreatic β-cells is essential for maintaining glucose homeostasis and preventing type 2 diabetes, a condition closely associated with aging." (PMID 41349796, 2025). "Although different pathogenic mechanisms cause type 1 diabetes (T1D) and type 2 diabetes (T2D), loss of insulin-producing β-cells is a contributing feature of both." (PMID 40885390, 2025). "In metabolic disease prevention, daily intake of 25–38 g reduces type 2 diabetes incidence risk by 18% (Lancet meta-analysis), a mechanism involving delayed glucose absorption and improved insulin sensitivity." (PMID 41515400, 2025). "IL-1β, a major pro-inflammatory cytokine, is critically involved in INS signaling alterations; in obese individuals, high IL-1β and IL-6 circulating levels represent an important independent risk for developing type 2 diabetes." (PMID 40940769, 2025). "A possible mechanistic basis is that these isoforms preferentially generate C16-ceramide, a species implicated in hepatic insulin resistance, steatosis, and inflammation and in the pathogenesis of obesity and type 2 diabetes." (PMID 41256541, 2025). "Disturbance in FOXO1 transcription causes insulin signaling to be blocked, driving gluconeogenesis and leading to excessive glucose production in Type 2 diabetes." (PMID 41030587, 2025). "Aging, type 2 diabetes, and obesity are all associated with changes in the metabolism of fatty acids (FAs); lipid buildup inside muscle cells is a major cause of muscle insulin resistance and ceramide formation." (PMID 39980914, 2025). "Previous human studies have identified predicted nonsynonymous variants in the PAM gene associated with reduced insulin secretion and the risk of type 2 diabetes (T2D)." (PMID 39137152, 2025). "This is very much different from the natural course of conventional type 2 diabetes, which is a progressive disease characterized by slow but relentless loss of insulin-producing β-cell functional mass over time." (PMID 39678649, 2025). "The aim of the current study was to evaluate knowledge and practices regarding insulin use among people with type 1 and type 2 diabetes in Jordan, as well as the factors associated with insulin use practice." (PMID 40471961, 2025). "Clinically, elevated HOMA-IR values indicate an impaired insulin response, suggesting a predisposition to metabolic disorders such as type 2 diabetes and cardiovascular disease." (PMID 40002771, 2025). "The DEG PALD1 is a negative regulator of insulin signaling in American Indians and is associated with type 2 diabetes in this population." (PMID 41465472, 2025). "Type 2 diabetes causes a disruption of this process by peripheral hyperinsulinemia, reducing the insulin transport into the brain." (PMID 41470842, 2025). "In conclusion, our findings reveal substantial heterogeneity in type 2 diabetes and prediabetes subtypes with disproportionately high prevalence of insulin-deficient subtypes." (PMID 40678231, 2025). "Additional work is needed to clarify the role of chronotype on the crosstalk between pancreatic β‐cells and insulin sensitive tissues in order to optimize treatments that lower type 2 diabetes risk in people with obesity." (PMID 40018087, 2025).
type 2 diabetes (continued). "At the other extreme, the MedDiet has consistently demonstrated beneficial effects on glycemic control, insulin sensitivity, blood pressure, and lipid profile, particularly in individuals with type 2 diabetes and high cardiovascular risk." (PMID 41515130, 2025). "Chronic inflammation impairs insulin signaling, reduces glucose uptake, and increases the risk of developing type 2 diabetes." (PMID 40362254, 2025). "Type I diabetes is caused by autoimmune destruction of pancreatic β-cells, resulting in loss of insulin secretion, while Type II diabetes primarily stems from insulin resistance, affecting how the body utilizes its endogenous insulin." (PMID 41383402, 2025). "Background/Objective: The single-nucleotide polymorphism (SNP) rs10830963 in the melatonin receptor 1B (MTNR1B) gene influences insulin secretion and glucose metabolism and has been associated with an increased risk of type-2 diabetes." (PMID 40428319, 2025). "Vegan and vegetarian diets are associated with improved insulin sensitivity, better glycemic control, and a lower risk of type 2 diabetes." (PMID 40871683, 2025). "Type 2 diabetes mellitus (T2DM) is a chronic metabolic disease characterized by hyperglycemia due to insulin secretion deficiency or resistance and impaired carbohydrate, lipid and protein metabolism." (PMID 40363900, 2025). "Metformin, prescribed medication for type 2 diabetes, and insulin, used for blood glucose regulation, are both associated with elevated glucose levels known to increase risk of cancer." (PMID 40961920, 2025). "DENN/MADD is known to mediate glucose-induced insulin secretion in pancreatic β-cells; disruption of this pathway can cause type II diabetes." (PMID 40812422, 2025). "Morning types typically have higher insulin sensitivity earlier in the day, while evening types show impaired glucose handling and greater risk of type 2 diabetes." (PMID 41305580, 2025). "Understanding the mechanisms linking OSAS to impaired insulin clearance is crucial for developing targeted preventive and therapeutic strategies, ensuring early intervention and reducing the risk of type 2 diabetes." (PMID 40365648, 2025). "Hyperinsulinemia, a well-established risk factor for type 2 diabetes, remains difficult to define due to variability in insulin assays." (PMID 40831565, 2025). "In summary, we confirm that SLC30A8 LoF is protective against type 2 diabetes, while partial LoF is associated with statistically significant improvements in glucose tolerance and insulin secretion." (PMID 41020949, 2025). "In contrast to type 2 diabetes, the pathophysiology is dominated by combined endocrine failure (e.g., deficient β-cell insulin and α-cell glucagon secretion) together with malabsorption from exocrine insufficiency and systemic inflammation." (PMID 41226286, 2025). "These individuals had already shown themselves to have beta cells susceptible to excess fat, and unsurprisingly first-phase insulin response decreased to the baseline type 2 diabetes level." (PMID 40316731, 2025). "For example, berries, green leafy vegetables, and cruciferous vegetables are abundant in antioxidants, which can improve insulin sensitivity and lower the risk of metabolic syndrome and type 2 diabetes." (PMID 40122387, 2025). "It has been implicated in insulin regulation and type 2 diabetes risk in both animal and clinical studies." (PMID 40830362, 2025). "Type 2 diabetes is an insulin-resistant state associated with an increase in free fatty acids, triglycerides, and LDL cholesterol, as well as a decrease in HDL cholesterol." (PMID 40142784, 2025). "Lower cardiovascular fitness was linked to reduced insulin sensitivity, which increased the risk of cardiovascular disease and type 2 diabetes." (PMID 40894483, 2025). "The LAP is strongly associated with insulin sensitivity in patients with impaired glucose tolerance or type 2 diabetes and effectively identifies subclinical vascular damage." (PMID 41470817, 2025).
type 2 diabetes (continued). "Coriobacteriaceae have been linked to benefits in insulin sensitivity in the prevention of the development of type 2 diabetes." (PMID 41165062, 2025). "Type 2 diabetes is a chronic disease marked by hyperglycemia; impaired insulin secretion by pancreatic β-cells is a hallmark of this disease." (PMID 38673770, 2024). "Rimonabant was able to reduce appetite thereby promoting weight loss, improved lipid profiles, and enhanced insulin sensitivity, potentially lowering the risk of type 2 diabetes." (PMID 39512900, 2024). "Other factors that are associated with reduced insulin sensitivity include advanced maternal age, a family history of type 2 diabetes (T2D), polycystic ovary syndrome, genetic factors, and physical inactivity." (PMID 39389786, 2024). "Multiple studies have shown that the occurrence of this polymorphism was associated with a lower risk of type 2 diabetes as well as improved insulin sensitivity in humans, suggesting that this amino acid change enhances the action of insulin." (PMID 39062500, 2024). "In type 2 diabetes (T2D), β cell death and dysfunction (or beta cell failure) are caused by excessive insulin demand and stress in insulin resistance conditions." (PMID 38811543, 2024). "Genetically proxied body mass index, fasting insulin levels, and type 2 diabetes partially mediated the associations of LST and MVPA with several gastrointestinal diseases." (PMID 38583262, 2024). "Insulin-antagonistic, counter-regulatory hormones have been implicated in the development of type 2 diabetes (T2D)." (PMID 37708362, 2024). "Type-2 diabetes mellitus is a chronic metabolic disorder characterized by insulin resistance and impaired insulin secretion, associated with an enhancement of blood glucose levels." (PMID 38440776, 2024). "DKA risk is also increased with SGLT2 inhibitors in adults with type 1 diabetes and insulin-deficient type 2 diabetes." (PMID 38907161, 2024). "Observational studies have linked reduced blood levels of VK to type 2 diabetes (T2D), implicating its role in glycemic regulation and insulin sensitivity." (PMID 39599583, 2024). "Adiposity has a recognized central role in the development of type 2 diabetes as higher BMI has been shown to induce low-grade inflammation and decrease insulin sensitivity, increasing the risk of hyperglycemia." (PMID 39148083, 2024). "Type 1 diabetes is caused by insulin destruction, while type 2 diabetes is caused by insufficient insulin secretion, leading to elevated blood glucose." (PMID 39650520, 2024). "For example, decreased insulin sensitivity and the development of type 2 diabetes are closely linked to this condition, due to the function of muscles to ensure energy homeostasis by regulating metabolism and insulin sensitivity." (PMID 39409095, 2024). "There was a mutually interdependent influence of hyperuricemia and type 2 diabetes on increased incidents as well as a reciprocal causative correlation between resistance to insulin and hyperuricemia." (PMID 39275283, 2024). "Type 2 diabetes liability and fasting insulin were inversely associated with apolipoprotein A1, total cholines, lipoprotein subfractions in high-density-lipoprotein and intermediate-density lipoproteins, and positively associated with aromatic amino acids." (PMID 38459184, 2024). "Studies in adults and babies born with low birth weight for gestational age indicate that resistance to insulin is a characteristic associated with low birth weight, regardless of confounding factors, such as a family history of type 2 diabetes and obesity." (PMID 39457235, 2024). "Higher protein diets have been shown to stimulate insulin secretion, which in the long term has been associated with an increased risk of type II diabetes." (PMID 39643829, 2024). "OT-R levels are higher in Type 2 diabetes, and there is an association of OXTR variants with insulin sensitivity and Type 2 diabetes." (PMID 38594674, 2024).
type 2 diabetes (continued). "Accordingly, insulin resistance disorders such as obesity, type 2 diabetes, and metabolic syndrome are closely linked to AD, which, in turn, is characterized by impaired insulin signaling in the brain and decreased levels of insulin and insulin receptors." (PMID 39656485, 2024). "Type 1 diabetes, also known as insulin-dependent diabetes, is linked to inadequate insulin secretion, while Type 2 diabetes, known as insulin-independent diabetes, is associated with reduced cell responsiveness to insulin." (PMID 38970639, 2024). "The findings underscore the importance of carefully managing factors such as insulin therapy and underlying conditions like type 2 diabetes to prevent hypoglycemic episodes in this population." (PMID 39735099, 2024). "Our analyses include a wide array of cardiovascular risk factors and uniquely analyze type 2 diabetes, insulin use, and oral hypoglycemic use independently." (PMID 39006603, 2024). "Weight gain caused by insulin therapy can be a major challenge for patients with type 2 diabetes who are already overweight." (PMID 39734678, 2024). "An increase in LDL-C has been found to be positively associated with insulin secretion, and inversely with the risk of type 2 diabetes." (PMID 38989003, 2024). "NAFLD has a close association with type 2 diabetes (T2D), high serum insulin level, abnormal glucose tolerance, visceral fat accumulation, dyslipidemia, and hypertension too." (PMID 39420901, 2024). "Chronic inflammation impairs insulin signaling, reducing glucose uptake and increasing the risk of developing type 2 diabetes." (PMID 39796335, 2024). "Hyperglycemia and dyslipidemia stimulate pro-inflammatory mechanisms, leading to IR and impaired insulin secretion, increasing the risk of developing type 2 diabetes (T2D) and weakening immune response against parasites." (PMID 39201314, 2024). "Despite opposing insulin sensitivity and cardiometabolic risk, both athletes and patients with type 2 diabetes have increased skeletal myocyte fat storage: the so-called “athlete’s paradox”." (PMID 38750012, 2024). "BCAAs and AAAs have long been associated with obesity, glucose, insulin (resistance), and type 2 diabetes." (PMID 38494119, 2024). "Estrogen therapy is linked to decreased fasting insulin and glucose levels, increased fat-free mass, and improved physical fitness in patients of Type 2 Diabetes." (PMID 39198906, 2024). "KCNJ15 has also been identified as a susceptibility gene to type II diabetes mellitus though the focus to date has been on pancreatic β cells where Kir4.2 function is proposed to inhibit glucose-stimulated insulin secretion." (PMID 39348460, 2024). "The association between insulin indices and some metabolic disorders including type 2 diabetes, low level of high-density lipoprotein (HDL) cholesterol and cardiovascular disease (CVD) has been previously reported." (PMID 38263222, 2024). "The findings indicate that, even in non-critically ill patients, careful management of factors such as insulin therapy and underlying conditions like type 2 diabetes is essential to prevent hypoglycemic episodes." (PMID 39735099, 2024). "Conversely, insufficient levels of VD have been linked to impaired insulin secretion and an increased risk of type 2 diabetes." (PMID 38910623, 2024). "This is important, especially in women with GDM whereby improvement in insulin sensitivity reduces the overall risk of type 2 diabetes and future CVDs." (PMID 39807464, 2024). "Insulin treatment was associated with higher DR prevalence (55.6%) than oral antidiabetic treatment (22.5%, p < 0.001) for type 2 diabetes patients." (PMID 39451664, 2024). "We used the risk ratio (RR) of type 2 diabetes to represent the clinical outcomes for cohort studies, while the biomarkers, including fasting blood glucose and insulin, HbA1C, and HOMA-IR, were utilized to show outcomes for RCTs." (PMID 38664726, 2024).
type 2 diabetes (continued). "The risk of type 2 diabetes is reduced by increasing insulin sensitivity in trained muscles and muscle glucose uptake induced by muscle contractions." (PMID 39730392, 2024). "Lung cancer is the leading cause of cancer-related deaths in the United States, and people with Type 2 Diabetes often use insulin therapy, which has been associated with increased lung cancer risk." (PMID 39001440, 2024). "Maintaining an active lifestyle aids in weight management, enhances insulin sensitivity, and decreases the risk of type 2 diabetes." (PMID 38920999, 2024). "Insulin therapy is common, and the association between insulin use in patients with uncontrolled type II diabetes mellitus, defined as having an HbA1C of more than 9 %, and cardiovascular sequelae is questionable." (PMID 39295783, 2024). "Latent autoimmune diabetes of adults (LADA) can also be misdiagnosed as type 2 diabetes, with a risk of delayed insulin initiation." (PMID 38910151, 2024). "Polyphenol-rich plant foods have been documented to mimic insulin’s effects on glucose metabolism and serve as effective inhibitors of crucial enzymes like α-amylase and α-glucosidase, which are linked to type 2 diabetes and tissue lipid peroxidation." (PMID 39451533, 2024). "Currently, several drug therapies, including hypoglycemic agents, insulin, and its analogues, are used to manage type 2 diabetes and reduce the risk of complications." (PMID 39728105, 2024). "Another study showed that abdominal fat thickness is an independent risk factor for type 2 diabetes, possibly due to the increase in insulin resistance in muscle tissue caused by free fatty acids and cytokines produced by abdominal fat." (PMID 38674203, 2024). "Decreased expression of miRNA-375 has demonstrated effectiveness in managing type 2 diabetes by lowering the apoptotic loss of pancreatic β cells and maintaining adequate insulin secretion in the body." (PMID 38805166, 2024). "Type 2 diabetes (T2D) represents a chronic metabolic condition characterized by insulin resistance and insufficient insulin production by pancreatic cells, associated with lifestyle factors such as inadequate diet and lack of physical activity." (PMID 38794296, 2024). "Certain miRNAs have been associated with processes relevant to type 2 diabetes (T2D), including apoptosis, response to cytokines, and insulin secretion." (PMID 38916841, 2024). "Research has demonstrated that Etv5 is an obesity-related transcriptional inhibitor of insulin secretion and is closely associated with obesity and type 2 diabetes." (PMID 39840059, 2024). "Type II diabetes is caused by defective insulin secretion and the reduced sensitivity of receptors on the cells to respond to insulin." (PMID 39165448, 2024). "At present, there are three potential mechanisms of association between type 2 diabetes and breast cancer, including the insulin pathway, insulin-like growth factor (IGF) pathway, and sex-hormone regulation." (PMID 38904041, 2024). "HRTs show promise in improving lipid profiles and insulin sensitivity, thus mitigating the risk of MetS and type 2 diabetes." (PMID 39124622, 2024). "Our results confirm findings from other studies, indicating that the presence of DR is associated with insulin therapy in individuals with type 2 diabetes." (PMID 39451664, 2024). "Previous studies have shown that injection of amylin reduced postprandial blood glucose levels in patients with type 2 diabetes and even cause severe hypoglycemia when combined with insulin." (PMID 38398700, 2024). "The COBLL1 gene has been implicated in human central obesity, fasting insulin levels, type 2 diabetes, and blood lipid profiles." (PMID 38699158, 2024). "INPP4B protects against metabolic syndrome and associated disorders and EXOC4 is involved in insulin-stimulated glucose transport and is associated with type II diabetes and fasting glucose." (PMID 38483771, 2024).